TRIM24 (tripartite motif containing 24)
Diseases named in the same sentence as TRIM24 in open-access papers (continued):
Sharing a sentence is not in itself a finding about the gene and the disease.
thyroid cancer (3 papers, 2021 to 2026). "On the other hand, TRIM24-associated transcription profiles were significantly depleted, with stem cell markers in HNSC (NES = −2.20), Thyroid Carcinoma (THCA) (NES = −2.18), and BLCA (NES = −1.90), which partially reflected the negative correlation of TRIM24 expression with stemness scores." (PMID 33810347, 2021).
anaplastic astrocytoma (2 papers, 2022 to 2024). "By screening a group of TRIM proteins, we found that ectopic expression of TRIM24 cooperated with HRasV12 to drive the transformation of human anaplastic astrocytoma (AA) into Ep‐GBM‐like tumors." (PMID 38828688, 2024). "Phosphorylated TRIM24 induces epigenome and transcription factor network reprogramming and consequently promotes HRasV12 anaplastic astrocytoma transforming into Epithelioid Glioblastoma‐like tumors." (PMID 38828688, 2024).
asthma (2 papers, 2015 to 2024). "Single nucleotide polymorphisms in cap methyltransferase 1 (CMTR1), tripartite motif containing 24 (TRIM24), and membrane associated guanylate kinase, WW and PDZ domain containing 2 (MAGI2) genes were found to be associated with variability in asthma exacerbations." (PMID 38630536, 2024). "No roles for TRIM24 have been described for asthma, respiratory disease, respiratory immune responses or corticosteroid use." (PMID 26734457, 2015).
epilepsy (2 papers, 2018 to 2025). A brain disorder characterized by episodes of abnormally increased neuronal discharge resulting in transient episodes of sensory or motor neurological dysfunction, or psychic dysfunction. "Given its related function, TRIM24 might play a similar role in the development of epilepsy." (PMID 29958461, 2018).
esophageal squamous cell carcinoma (2 papers, 2016 to 2024). Esophageal squamous cell carcinoma (ESCC) is a type of esophageal carcinoma (EC) that can affect any part of the esophagus, but is usually located in the upper or middle third. "Notably, TRIM24 mRNA and protein levels are reduced in esophageal squamous cell carcinoma tissues, with TRIM24 protein level being considered as an independent favorable prognostic factor for overall survival in esophageal squamous cell carcinoma patients." (PMID 39160596, 2024).
lung adenocarcinoma (2 papers, 2019 to 2023). A carcinoma that arises from the lung and is characterized by the presence of malignant glandular epithelial cells. "Adenoviruses encoding Cas9 and sgRNA pairs inducing the Kif5b-Ret and Trim24-Ret rearrangements were intratracheally instilled into mice and yielded lung adenocarcinomas." (PMID 37470475, 2023).
osteosarcoma (2 papers, 2023 to 2024). A usually aggressive malignant bone-forming mesenchymal neoplasm, predominantly affecting adolescents and young adults. "A recent study showed that BMP8A can diminish chemotherapy sensitivity in ccRCC by promoting Nrf2 phosphorylation and activating TRIM24, implying its potential role in drug resistance in osteosarcoma." (PMID 37964984, 2023). "A screening of 32 human bromodomain-containing proteins, including all four TIF1 family members, demonstrated that TRIM24, TRIM28, and TRIM33 localized to damage sites in the U2OS osteosarcoma cell line following laser microirradiation, while TRIM66 did not exhibit the same behavior." (PMID 39160596, 2024).
ovarian serous cystadenocarcinoma (2 papers, 2021 to 2022). A malignant serous cystic epithelial neoplasm arising from the ovary. "Compared to normal ovary tissues, TRIM24 mRNA expression had a significant enhancement in ovarian serous cystadenocarcinoma (TCGA Ovarian database: P = 8.71E-6, t = 9.27, and TCGA Ovarian 2 database: P = 4.39E-70, t = 20.198)." (PMID 35105347, 2022). "Data from Oncomine show that the TRIM24 mRNA expression was obviously elevated in ovarian serous cystadenocarcinoma compared to normal ovary tissues." (PMID 35105347, 2022).
renal carcinoma (2 papers, 2020). A carcinoma arising from the epithelium of the renal parenchyma or the renal pelvis. "Seven genes (TRIM8, TRIM11, TRIM16, TRIM24, TRIM27, TRIM32, and PML) were expressed in different renal cancer cell lines through the KM expression website." (PMID 33173411, 2020).
steatosis (2 papers, 2016 to 2022). Increased lipid within the cytoplasm of cells. "TRIM24 deficiency would result in hepatocellular lesions, steatosis, fibrosis and carcinoma, which are caused by imbalanced lipid metabolism and inflammation." (PMID 35806477, 2022).
acute myeloid leukemia (1 paper, 2022). Acute myeloid leukemia (AML) is a group of neoplasms arising from precursor cells committed to the myeloid cell-line differentiation. "PROTAC 11 recruits VHL to cause the effective and selective degradation of TRIM24 in human acute myeloid leukemia MOLM-13 cells." (PMID 36142231, 2022). "This study proposes TRIM24 as a fresh target for acute myeloid leukemia creation of drugs, providing a new avenue for “undruggable targets”." (PMID 36142231, 2022).
breast tumor (1 paper, 2019). "To this end, we collected CD11b+ macrophages from breast tumor and adjacent normal tissues from the same cancer patient and examined expression of the TRIM24 and M2 genes in six patients." (PMID 31554795, 2019). "Decreased TRIM24 expression and increased expression of the M2 genes CCL17 and IRF4 were detected in macrophages isolated from breast tumors compared with their levels in adjacent normal tissues." (PMID 31554795, 2019).
calcification (1 paper, 2012). Process by which organic tissue becomes hardened by the physiologic deposit of calcium salts. "In addition, arterial calcifications and expression of vitamin D receptor targets were increased in mice lacking TRIM24, showing that TRIM24 could prevent calcification of arteries by decreasing the activity of the vitamin D signaling pathway." (PMID 22666376, 2012).
carcinosarcoma (1 paper, 2021). A malignant tumor composed of a mixture of carcinomatous and sarcomatous elements. "Next, the association between TRIM24-driven metaplastic carcinosarcoma tumors and a previously reported human MpBC gene expression signature was calculated using GSEA12." (PMID 34508101, 2021). "CyTOF analysis revealed that Trim24COE metaplastic carcinosarcomas exhibited high levels of TRIM24, phospho-PI3K (pPI3K), phospho-AKT (pAKT), and mTOR within the same spatial orientation." (PMID 34508101, 2021). "We used Reverse Phase Protein Array (RPPA) to quantify specific proteins in TRIM24-driven metaplastic carcinosarcomas compared to MMTV-Cre mammary glands." (PMID 34508101, 2021). "Comparison of Trim24COE metaplastic carcinosarcoma morphology, TRIM24 protein levels and a derived Trim24COE gene signature reveals strong correlation with human MpBC tumors and MpBC patient-derived xenograft (PDX) models." (PMID 34508101, 2021). "This analysis shows a consistent overlap at gene expression level between human MpBC tumors and TRIM24-driven metaplastic carcinosarcoma." (PMID 34508101, 2021). "We developed a TRIM24-driven metaplastic carcinosarcoma gene signature and compared it to human MpBC tumor global gene expression to derive a TRIM24 metaplastic score for each MpBC patient in the cohort reported in this study." (PMID 34508101, 2021). "The TRIM24-driven metaplastic carcinosarcoma cell line showed higher chromatin accessibility at specific sites along the Met gene region, compared to the MMTV-Cre-control cell line." (PMID 34508101, 2021). "Overall, these results suggest that TRIM24-driven mouse metaplastic carcinosarcomas exhibit significant similarities to human MpBC tumors by gene expression and hallmark pathway profiling, offering an animal model of human triple-negative MpBC suitable for development of potential therapeutics." (PMID 34508101, 2021). "Additionally, EMT scores, calculated by an ssGSEA algorithm, showed significant differences between TRIM24-driven metaplastic carcinosarcoma tumors and TRIM24-driven carcinoma tumors." (PMID 34508101, 2021). "Global gene expression analyses of TRIM24-driven carcinosarcomas were used to generate a TRIM24 metaplastic signature that revealed highly up-regulated glycolysis, EMT and PI3K pathways, the latter confirmed by global and single-cell analysis of tumor protein levels." (PMID 34508101, 2021). "TRIM24 aberrantly activates c-MET-PI3K-mTOR pathways, nominating pharmacological approaches that proved effective in inhibition of metaplastic carcinosarcoma primary cell viability." (PMID 34508101, 2021). "Together, we show that TRIM24-mediated, epigenetic activation of c-Met is disrupted by selective inhibitors, Crizotinib and PHA-665752, in a dose-dependent manner in primary metaplastic carcinosarcoma tumor cells." (PMID 34508101, 2021).
cardiac hypertrophy (1 paper, 2024). "MYC and TRIM24, both predicted to be activated by optoVNS, are important cardiac transcription factors involved in cardiac development and both play important roles in modulation of cardiac hypertrophy." (PMID 38047311, 2024).
cardiomyopathies (1 paper, 2025). "These insights not only expand our understanding of the multifaceted functions of TRIM24 but also suggest its potential as a therapeutic target for cardiac dysfunction, warranting further investigation into its mechanistic roles in human cardiomyopathies." (PMID 40598158, 2025).
cervical cancer (1 paper, 2022). A primary or metastatic malignant neoplasm involving the cervix. "Silencing TRIM24 expression in cervical cancer can inhibit the epithelial mesenchymal transition by regulating NF -κB expression and Akt pathways." (PMID 35105347, 2022).
colorectal tumor (1 paper, 2020). "We found that TRIM24 protein was more highly expressed in colorectal tumor tissues than in paired peri‐tumoral tissues." (PMID 32677374, 2020).
EBV infection (1 paper, 2023). "As expected, prominent interactions were seen with TRIM28 and TRIM24, confirming that either dimeric or trimeric interactions occur between these proteins and TRIM33 in lytic EBV infection." (PMID 37410772, 2023). "While TRIM28 has been previously shown to repress BZLF1 expression, potential roles of TRIM24 and TRIM33 in restricting EBV infection have not been investigated." (PMID 37410772, 2023).
fibrosarcoma (1 paper, 2022). A malignant mesenchymal fibroblastic neoplasm affecting the soft tissue and bone. "Fibrosarcomas also exhibited the greatest number of transcription factors among the top 25 most significantly upregulated genes, including TRIM24 which acts as an oncogene when overexpressed in several human cancer types." (PMID 36099287, 2022).
malaria (1 paper, 2020). Malaria is a serious and sometimes fatal disease caused by a parasite that commonly infects a certain type of mosquito which feeds on humans. "Predicted inhibited upstream regulators of monocyte gene expression in subpatent primary infection included MAPK1, IL1RN and TRIM24, which overlapped with regulators predicted to be inhibited in malaria‐naive volunteers experiencing symptomatic malaria following P. falciparum sporozoite infection." (PMID 32566226, 2020).
neuroepithelial tumors (1 paper, 2024). "We report a series of three cases of infant-type hemispheric glioma (IHG) involving three infants diagnosed with neuroepithelial tumors of the cerebral hemispheres harboring a novel, recurrent TRIM24::MET fusion." (PMID 38902810, 2024).
pulmonary arterial hypertension (1 paper, 2022). Pulmonary arterial hypertension (PAH) is a group of diseases characterized by mean pulmonary artery pressure >20 mmHg and elevated pulmonary arterial resistance leading to right heart failure. "In the current study, we found TRIM24 was increased in PAs of chronic hypoxia-pulmonary arterial hypertension (CH-PAH) mice and hypoxia-challenged PASMCs." (PMID 35653796, 2022). "The current study was aimed to reveal the role of TRIM24 in proliferation and migration of PASMCs during the development of pulmonary arterial hypertension (PAH)." (PMID 35653796, 2022).
rectal adenocarcinoma (1 paper, 2014). "We also detected a single TRIM24–BRAF fusion in rectal adenocarcinoma." (PMID 25204415, 2014).
triple-negative breast carcinoma (1 paper, 2023). An invasive breast carcinoma which is negative for expression of estrogen receptor (ER), progesterone receptor (PR), and human epidermal growth factor receptor 2 (HER2). "For example, in triple-negative breast cancer, KAT6A promotes interactions between SMAD3 and TRIM24 by mediating SMAD3 acetylation and inhibiting interactions between SMAD3 and TRIM33, thereby promoting tumor progression by regulating the immune microenvironment." (PMID 36611207, 2023).
Type II diabetes (1 paper, 2025). "KEGG analysis further implicated TRIM24 in cancer-related pathways, Type II diabetes, adrenergic signaling (RNO04261), and PI3K-AKT signaling." (PMID 40598158, 2025).
tumor (105 papers, 2011 to 2025). "The tumour-related functions of TRIM24 are linked to its role as a transcriptional co-regulator in the nucleus." (PMID 35803934, 2022). "The tumor-promoting effect of TRIM24 is associated with its pro-proliferative role in different cancer cells." (PMID 35653796, 2022). "TRIM24-associated transcription profiles were significantly enriched with stem cell markers (Wong ESC core gene set) in only 10 tumor types, and the normalized enrichment score (NES) for this signature ranged from 3.15 (SARC) to 4.99 (GBM)." (PMID 33810347, 2021). "To investigate the association between TRIM24 activity and metaplastic tumors, we analyzed previously published tumor expression data sets." (PMID 34508101, 2021). "KAT6A directly binds to and acetylates SMAD3 at K20 and K117, which promotes SMAD3 association with oncogenic chromatin modifier TRIM24 and disrupts its interaction with tumor suppressor TRIM33." (PMID 34392614, 2021). "High expression of TRIM24 has been associated with a higher tumour grade in prostate cancer and was proposed to be an independent biomarker for prognosis." (PMID 32731534, 2020). "Accordingly, the myeloid cell's Trim24 deficiency impaired the tumor infiltration of IFNγ-producing CD4+ and CD8+ effector T cells, suggesting that Trim24 deficiency impaired antitumor immunity through suppressed Stat6 acetylation in TAMs." (PMID 31554795, 2019). "Significant association was found between TRIM24 overexpression and tumor-node-metastasis (TNM) stage (p = 0.0034) and T stage (p = 0.0048)." (PMID 29862279, 2018). "Recently, a growing number of studies have reported that expression of TRIM24 protein is associated with tumor progression and survival in various cancers." (PMID 29862279, 2018). "TRIM24 was originally named transcription intermediary factor 1-alpha (TIF1α), which was associated with cellular proliferation and was an oncogene in tumor development." (PMID 24409330, 2014). "Meanwhile, TRIM24 can bind chromatin and the estrogen receptor to activate estrogen-dependent genes associated with cell proliferation and tumor development in breast." (PMID 23717505, 2013). "TRIM24 also binds chromatin and oestrogen receptor to activate oestrogen -dependent genes which were associated with cellular proliferation and tumor development." (PMID 22666376, 2012). "Furthermore, both TRIM24 and TRIM28 expression associated with angiogenesis signatures in tumour samples, and conditioned media from TRIM24 and TRIM28-silenced cancer cells inhibited endothelial cell proliferation and formation of vascular tube structures." (PMID 40411304, 2025). "In addition, TRIM24 expression was associated with tumor T stage, indicating that TRIM24 predicted the depth of tumor invasion." (PMID 41430038, 2025). "This review comprehensively explores the functional properties TRIM24 in cancer cells, providing an updated overview of its current status in cancer research and seeking insights into the profound mechanisms driving tumor progression, as well as potential therapeutic targets associated with TRIM24." (PMID 39160596, 2024). "Notably, TRIM24 is a co-activator of estrogen receptor-α, facilitating the activation of estrogen-dependent genes linked to cellular proliferation and tumor development." (PMID 39160596, 2024). "TRIM24 binds chromatin and the estrogen receptor to activate estrogen-dependent genes linked to cellular proliferation and tumor development, with its PHD-bromodomain providing a structural rationale for chromatin activation through a noncanonical histone signature." (PMID 39160596, 2024).